LATS1 (large tumor suppressor kinase 1)
Diseases named in the same sentence as LATS1 in open-access papers (continued):
Sharing a sentence is not in itself a finding about the gene and the disease.
tumor (continued). "We hypothesized that LATS1 expression was closely correlated with tumour invasion of LAC, and 17-AAG as a HSP90 inhibitor could impair growth and invasion of LAC cells via regulation of the LATS1/YAP signalling." (PMID 25712415, 2015). "Although the functionality of the LATS1 protein with the genotyped SNPs/variants remains unidentified, the results reveal an association of these missense variants with the peri-tumoral and tumor tissues that may impact the tumor suppressor activity of LATS1." (PMID 25628642, 2014). "For example, MOB1-deficient animals develop the broadest range of tumours amongst all mice carrying manipulations of Hippo signalling components, suggesting that factors other than MST1/2, SAV, or LATS1/2 might play additional key roles." (PMID 25097725, 2014). "It is therefore possible that WWP1, with four WW domains, may compete with YAP and TAZ for LATS1 binding to control the levels of tumor suppressor LATS1." (PMID 23573293, 2013). "LATS1 is a ser/thr kinase and novel tumor suppressor down-regulated in various human cancers." (PMID 23573293, 2013). "Interestingly, previous studies also showed that LATS1 suppresses tumor cell growth by interacting with two WW domains of its substrates YAP and TAZ using its PPxY motifs." (PMID 23573293, 2013). "Furthermore, loss of LATS1/2 or overexpression of YAP is sufficient to reprogram cancer stem cells to attenuate Wnt signaling, thereby suppressing tumor growth in organoids, patient-derived xenografts, and mouse models of primary and metastatic colorectal cancer (CRC)." (PMID 38566194, 2024). "However, LATS1/2 deletion has the opposite effect and enhances the immunogenicity of tumor cells." (PMID 39174509, 2024). "However, it remains to be determined whether the PIP5Kγ/Merlin/LATS1 signaling axis plays a functional role in tumor progression." (PMID 37834234, 2023). "Additionally, a tumor-promoting long non-coding RNA (lncRNA) known as small nucleolar RNA host gene 9 (SNHG9) has been found to identified to drive the liquid droplet formation of Large Tumor Suppressor Kinase 1 (LATS1) and inhibits the Hippo pathway." (PMID 37580790, 2023). "The Hippo signaling pathway is a highly conserved tumor suppressor pathway, mainly including Ste20-like kinase 1 (MST1) and large tumor suppressor 1 (LATS1), Yes associated protein 1 (YAP1) and its analog TAZ, and the regulatory subunits of MST1 and LATS1, MOB1 and SAV1." (PMID 35810157, 2022). "However, Lats1/2 deletion led to regression of three murine syngeneic tumor models." (PMID 35798829, 2022). "Moreover, in vitro gain of function and loss of function tests revealed that silencing LATS1 dramatically increased the CRC cell's potential to proliferate and migrate, whereas LATS1 overexpression did the opposite, signifying the tumor-suppressive effects of LATS1." (PMID 35003351, 2021). "Notably, alterations of LATS1/2 expression in tumor cells can be modulated by microRNAs (miRs)." (PMID 33467099, 2021). "Furthermore, LATS1 protein expression levels in CRC tumor tissues with larger tumor sizes (≥5 cm), deeper invasion (T3-4), positive lymph node metastasis (LNM), or advanced tumor-node-metastasis (TNM) stage (III-IV) were lower significantly as compared to control groups." (PMID 35003351, 2021). "However, we observed that LATS1/2 cKO animals depleted of both copies of YAP1 exhibit a significant reduction (p < 0.001, Dunn’s multiple comparisons test) in average tumour size compared with LATS1/2 cKO animals, indicating that level of YAP expression impacts tumour size." (PMID 32404936, 2020). "However, tumour formation was suppressed at P20 in LATS1/2 cKO YAP1f/f TAZf/+ mice (n = 3)." (PMID 32404936, 2020).
tumor (continued). "Therefore, we examined the levels MST1/2 and LATS1 kinases in ±DDR tumours +COL1." (PMID 32047176, 2020). "Therefore, the role of LATS1/2 in a tumor microenvironment remains controversial." (PMID 32983971, 2020). "To further determine whether FRY's interaction with the Hippo/YAP signaling pathway contributes to the observed FRY's tumor suppressive function, we used a siRNA targeting the LATS1 mRNA and reduced endogenous LATS1 protein levels by about 85% in the 231FRY cells (231FRY/LATS1KD)." (PMID 31824855, 2019). "Deficiency of Hippo pathway components such as kinases LATS1/2 (large tumor suppressor 1 and 2), effector YAP (Yes-associated protein), and transcriptional co-activator TAZ (WW domain-containing transcription regulator 1) could promote anti-tumor immunity." (PMID 30594216, 2018). "The localization of the MST1/2 and LATS1/2, whether it is cytoplasmic or nuclear, may impact the efficacy of the neoadjuvant therapy in breast cancer; being protective when expressed in the cytoplasm of tumor cells and in tumor-infiltrating lymphocytes." (PMID 29932172, 2018). "Mutations in Merlin and LATS1/2 may occur only in specific tumor types, such as mesothelioma, schwannomas, and meningiomas, but are not observed in most tumor types displaying elevated YAP/TAZ activity." (PMID 30101371, 2018). "Here, we reported that DUXAP10 could not only repress tumor suppressors LATS1 and KLF2 transcription through epigenetic modification by interacting with PRC2 and LSD1, also can regulate β-catenin mRNA stability by recruiting RNA binding protein HuR at post-transcriptional level in GC cells." (PMID 29374493, 2018). "Similarly, Lats1/2 deletion in mouse kidney leads to loss of nephron formation, but not tumor formation." (PMID 29673177, 2018). "Thus, tumor suppressors such as LATS1 may constrain the inherent plasticity of luminal progenitor cells, and their loss may augment plasticity in the context of tumorigenesis." (PMID 30456386, 2018). "We found that both of miR-424 high expression and LATS1 low expression were associated with pathological stage, OS and recurrence of GC patients, and miR-424 but not LATS1 gene was an independent prognostic factor for tumor recurrence of GC, suggesting a potential diagnostic marker for GC patients." (PMID 28893265, 2017). "However, LATS1 null animals develop tumours, and immortalised LATS2 null MEFs display loss of contact inhibition, indicating that LATS1/2 might function as tumour suppressors in mammals." (PMID 23985307, 2013). "In this study, we demonstrated that ANLN contributed to ICC growth via the RhoA/LATS1/YAP1 axis, establishing a link between ANLN and the Hippo pathway, which broadened the understanding of the role of ANLN in tumor." (PMID 41513610, 2026). "Collectively, our results support the idea that overexpression of DCLK1 promotes a stem cell-like phenotype by inducing LATS1-mediated YAP signaling activation, ultimately leading to tumor growth and progression in PCa." (PMID 39781521, 2025). "Collectively, our results support the idea that overexpression of DCLK1 promotes the acquisition of a stem cell-like phenotype by inducing large tumor suppressor homolog 1 (LATS1)-mediated YAP signaling activation, ultimately leading to tumor growth in PCa." (PMID 39781521, 2025). "In‐line with their tumor‐suppressive roles, reduced expression or activity of MST1/2 and LATS1/2 leads to metastasis in a subset of cancers." (PMID 40895190, 2025). "Recent studies have unveiled the “dual-module” signal transduction model of the Hippo pathway (HPO1 and HPO2), which cooperatively regulates LATS1/2 and YAP/TAZ activities, influencing cell fate, organ size, and tumor progression." (PMID 40612350, 2025). "Western blot analysis showed that RGD treatment increased the level of MST1/2, LATS1 and YAP phosphorylation but markedly reversed the elevated levels of FAK, SRC and AKT phosphorylation induced by VPS35 overexpression in tumour cells." (PMID 37950040, 2024).
tumor (continued). "Regarding the Hippo pathway, LATS1 and LATS2 are tumor suppressors that inhibit the oncogenic nuclear function of YAP/TAZ and TEAD." (PMID 38920690, 2024). "To validate our findings in vivo, we subcutaneously injected MEF Lats1/2 KO cells stably expressing TSSK1B WT and TSSK1B mutant (T174A) cells into BALB/c nude mice (N = 6) and monitored tumor development." (PMID 38245531, 2024). "The Hippo pathway consists of four tumor suppressors: SAV1, MST1/2, LATS1/2, and MOB kinase activators." (PMID 38920690, 2024). "In terms of the mechanism, we found that miR-21-5p carried by TAM-EVs activated HIF-1α in ECs through VHL and LATS1, forming a YAP1/HIF-1 positive loop, which plays a crucial role in promoting tumor angiogenesis." (PMID 38602536, 2024). "Previous studies have demonstrated that essential elements of the Hippo pathway, including MST1/2, LATS1/2, YAP/TAZ, and TEAD, play important roles in innate and adaptive immunity against tumor cells." (PMID 38499647, 2024). "Hippo signaling pathway, as a highly conserved tumor suppressor pathway, mainly included mammalian Ste20-like kinases 1/2 (MST1/2) and large tumor suppressor 1/2 (LATS1/2), YAP and/or its paralog TAZ." (PMID 36594102, 2023). "Immunohistochemistry showed that S1PR1 and p-histone H3 (marker of proliferation) protein levels were significantly decreased, whereas LATS1, LATS2, P62, and cleaved caspase-3 protein levels were significantly increased in S1PR1 knockout tumor tissue." (PMID 37828220, 2023). "As a tumor suppressor, NF2 interacts with and recruits the kinase LATS1 to the plasma membrane, which leads to the subsequent phosphorylation of LATS1 and the cytoplasmic retention of YAP25." (PMID 37080959, 2023). "Although both our current work and previous study have shown that SRC kinase could inhibit the Hippo tumor suppressor pathway through tyrosine phosphorylation of LATS1 in a YAP1-dependent manner, we still observed the increased TEAD-associated transcriptional activity in LATS1/2 knockdown cells." (PMID 36633714, 2023). "Expression of the SuperHippo minigene distinctly activates LATS1/2 activity, leading to complete inactivation of YAP/TAZ and effective inhibition of tumorigenesis in multiple tumor models." (PMID 37799806, 2023). "As a tumor promoter, YAP is under negative regulation by the Hippo kinase cascade, namely by its phosphorylation on multiple sites, including S127 by the LATS1/2 kinases, which promotes its cytoplasmic retention and subsequent degradation." (PMID 37858338, 2023). "When the expression or activity of S1PR1 is inhibited, PDK1 expression is decreased and LATS1/1 is activated, leading to YAP inactivation and tumor cell senescence." (PMID 37828220, 2023). "For instance, overexpression of miR-29c-3p in HCC can activate large tumor suppressor gene 1 (LATS1) expression and demethylation of LATS1 via DNMT3B, thereby impeding HCC cell tumor growth and migration both in vitro and in vivo." (PMID 36246623, 2022). "Hippo signaling is composed of tumor suppressors MST1/2 and LATS1/2, which regulate the activity of YAP/TAZ to suppress gene expression by the TF TEAD." (PMID 35017636, 2022). "It was recently reported that hydrogen peroxide inhibited tumor mortality by phosphorylating MST1, an upstream regulator of LATS1 and YAP." (PMID 35182054, 2022). "LATS1 and LATS2 are serine/threonine kinases that are direct negative regulators of YAP, playing a pivotal role in organ size control and tumor suppression by restricting proliferation and promoting apoptosis." (PMID 33477668, 2021).
tumor (continued). "Taken with other Hippo pathway members (NF2, LATS1 and LATS2), 50% of tumours had at least one lesion of this pathway." (PMID 34580349, 2021). "Previous evidence also demonstrated that LATS1/LATS2 deletion in tumors, which activates YAP signaling, induced increased tumor immunogenicity, leading to tumor destruction by enhancing anti-tumor immune responses." (PMID 33805359, 2021). "Other tumor suppressor genes, often altered in MPM patients, are LATS1/2, negative regulators of the Hippo-YAP pathway, whose deletion improved tumor immunogenicity together with an enhanced anti-tumor immune response." (PMID 34199722, 2021). "Lastly, Cucurbitacin B, a triterpene substance derived from Cruciferae and Cucurbitaceae was reported to increase LATS1 generation and reduce the expression of YAP, CYR61, and c-myc in tumor cells." (PMID 33924049, 2021). "The relationship between LATS1 protein expression and clinicopathological features in CRC tumor tissues was then investigated further." (PMID 35003351, 2021). "Specifically, NKX2–2-AS1 functions as a miRNA sponge to sequester miR-103, miR-107 and miR-548m, thereby maintaining the expression of their tumor-suppressive targets BTG2 (BTG anti-proliferation factor 2), LATS1 (large tumor suppressor kinase 1) and LATS2." (PMID 34316694, 2021). "The Hippo pathway comprises several tumor suppressors, including Mst1/2, Sav1/WW45, Lats1/2, and Mob1, which act as kinases that phosphorylate and inactivate of YAP." (PMID 32219176, 2020). "We found that MST2 (~60 kDa) (third panel from the top, p = 0.029), and LATS1 (~140–150 kDa) (p = 0.029) were both significantly downregulated in +DDR1b tumours when compared to −DDR1 tumours." (PMID 32047176, 2020). "The upstream components of the Hippo-pathway including MST1/2, LATS1/2, NDR1/2, Merlin, and RASSFs have been identified to be tumor suppressors." (PMID 32174922, 2020). "The core upstream components of the Hippo pathway comprise several tumour suppressors, including Mst1/2, Sav1/WW45, Lats1/2, and Mob122." (PMID 32661222, 2020). "Deletion of YAP1’s negative regulators LATS1 and LATS2 kinases in NEX-Cre lineage in double conditional knockout mice also generates similar tumours, which are rescued by deletion of YAP1 and its paralog TAZ." (PMID 32404936, 2020). "Focusing on a limited set of Hippo core components, we found that both +DDR/+COL1 tumours displayed a significant downregulation of MST2, while +DDR1b tumours also showed reduced levels of LATS1 and MST1." (PMID 32047176, 2020). "LATS1 is one of family proteins of large tumor suppressor (LATS) and has been proposed to be a tumor suppressor." (PMID 32429941, 2020). "In 2012, Zhao and Coll suggested the molecular mechanism by which YAP controls tumor cell survival: The kinases LATS1/2 regulate YAP activation and thus its involvement in tumor cell survival." (PMID 32164350, 2020). "Immunoblot analyses of the ±DDR/−COL1 tumours revealed that neither DDR1b nor DDR2 expression altered the levels of either YAP1 and its phosphorylated forms, MST1 and MST2, LATS1 or KIBRA, when compared to tumours with repressed DDRs (+DOX)." (PMID 32047176, 2020). "The Hippo pathway is a tumor suppressor pathway consisting of multiple proteins, including MST1/2, MOB1 and large tumor suppressor 1/2 (LATS1/2)." (PMID 30710319, 2019). "Mechanistically, PVT1 lncRNA knockdown increased phosphorylated LATS1 and phosphorylation of YAP1 which led to inactivated YAP1 leading to tumor growth inhibition." (PMID 31601234, 2019).
tumor (continued). "LATS1 and LATS2 kinases are evolutionarily conserved tumor suppressors, which share ~50% and 85% amino acid sequence identity between the full proteins and the kinase domains, respectively." (PMID 31848340, 2019). "Large tumor suppressor (LATS) family proteins LATS1 and LATS2 have been proposed to be tumor suppressors." (PMID 31586262, 2019). "Of note, MST1/2 and LATS1/2, the upstream kinases of the Hippo pathway, can regulate YAP phosphorylation as tumor suppressors." (PMID 30961610, 2019). "Both LATS1 and LATS2, are deregulated in various human cancers and correlate with tumor progression." (PMID 31391070, 2019). "In three different murine syngeneic tumour models (B16, SCC7 and 4T1), knockout of LATS1/2 in tumour cells inhibits proliferation." (PMID 28782275, 2018). "In our previous study we found at both mRNA and protein levels that LATS1 gene expression was downregulated and YAP1 expression upregulated in ccRCC tumor tissues in comparison to corresponding samples of unaltered kidney tissues." (PMID 29850494, 2018). "In contrast with conventional Lats1/2 tumor suppressor functions, it was recently demonstrated that, in different murine syngeneic tumor models (B16, SCC7, and 4T1), Lats1/2 exert an oncogenic function reducing tumor immunogenicity." (PMID 28467351, 2017). "The scaffold protein RASSF1A is an important tumor suppressive regulator of the Hippo kinases MST1/MST2 and the large tumor suppressor kinases LATS1/LATS2." (PMID 29179447, 2017). "The Hippo tumor suppressor pathway is essential for development and tissue growth control, encompassing a core cassette consisting of the Hippo (MST1/2), Warts (LATS1/2), and Tricornered (NDR1/2) kinases together with MOB1 as an important signaling adaptor." (PMID 28947795, 2017). "Both LATS1 and LATS2 as tumor suppressors are part of hippo signaling pathway which has profound effects on normal cell fate and tumorigenesis." (PMID 26942001, 2016). "Then, we demonstrated that 17-AAG inhibition of LAC proliferation and invasion depended on the activity of LATS1 in LAC cells, suggesting a novel molecular mechanism of 17-AAG in tumour therapy." (PMID 25712415, 2015). "Furthermore, our present finding showed that, 17-AAG inhibited LAC cell growth and invasion with the decreased expression of Ki-67 and MMP-2, suggesting that LATS1/YAP signalling might mediate 17-AAG suppression of tumour growth and invasion via regulation of Ki-67 and MMP-2 expression in LAC cells." (PMID 25712415, 2015). "More specifically, they showed that ILK inhibition in human tumour cells results in MST1 and LATS1 activation with concomitant inactivation of YAP/TAZ activities." (PMID 25097725, 2014). "Taken together, the data presented above support the speculation that overexpression of DCLK1 promotes stem cell-like characteristics by inducing LATS1-mediated YAP signaling activation, ultimately leading to tumor growth and progression in PCa." (PMID 39781521, 2025). "Unfortunately, targeting Hippo core kinase components MST1/2 or LATS1/2 is not a viable option as this would promote tumor development." (PMID 40869130, 2025). "In contrast, the Hippo mechanism, a key pathway in regulating cell proliferation and apoptosis, plays a role in cancer inhibition by activating LATS1/2, which, in turn, inhibits YAP/TAZ entry into the nucleus and induces the expression of tumor-growth-related genes." (PMID 41516111, 2025). "It was reported previously that YAP activation unexpectedly enhanced anti-tumor immunity; it is possible that LATS1/2 deletion in mouse tumor cell models (B16, SCC7, and 4T1) in that study did not upregulate the immune checkpoints." (PMID 40940864, 2025).